SGCB (sarcoglycan beta)
Description:
Component of the sarcoglycan complex, a subcomplex of the dystrophin-glycoprotein complex which forms a link between the F-actin cytoskeleton and the extracellular matrix.
Synonyms: SGC; A3b; LGMD2E; LGMDR4
Tractability: Antibody: its Gene Ontology location is reachable by antibodies, with high confidence; UniProt places it where antibodies can reach, with medium confidence; UniProt predicts a signal peptide or a membrane-spanning region. PROTAC: ubiquitination databases record sites on it.
Gene: Protein-coding gene on chromosome 4 (52,020,706 to 52,038,299, reverse strand). Ensembl gene ENSG00000163069.
Subcellular location: Cell membrane, sarcolemma; Cytoplasm, cytoskeleton
Subcellular location (Human Protein Atlas): Cytosol
Pathways (Reactome):
Extracellular matrix organization: Formation of the dystrophin-glycoprotein complex (DGC)
Gene Ontology:
Molecular function: protein binding
Biological process: camera-type eye development; muscle organ development
Cellular component: dystrophin-associated glycoprotein complex; endoplasmic reticulum membrane; Golgi membrane; neuromuscular junction; plasma membrane; sarcoglycan complex; sarcolemma; cytoskeleton; dystroglycan complex; membrane
Genetic constraint (gnomAD): Loss-of-function variants: 17 observed, 19.83 expected, observed/expected ratio (o/e) 0.86, 90% interval 0.59 to 1.29. The upper end of that interval is the gene's LOEUF score, 1.29, which puts it in group 5 of 6, group 1 being the genes least tolerant of losing a copy. Missense variants: 391 observed, 368.85 expected, observed/expected ratio (o/e) 1.06, 90% interval 0.98 to 1.15. Synonymous variants: 137 observed, 127.14 expected, observed/expected ratio (o/e) 1.08, 90% interval 0.94 to 1.24.
Gene-disease validity (ClinGen):
ClinGen rates the evidence that SGCB causes each of these diseases.
autosomal recessive limb-girdle muscular dystrophy (autosomal recessive): Definitive. Autosomal recessive form of limb-girdle muscular dystrophy.
Homologues: Orthologues: chimpanzee SGCB (99% identical), dog SGCB (97% identical), mouse Sgcb (95% identical), pig SGCB (95% identical), rat Sgcb (94% identical), guinea pig SGCB (93% identical), rabbit SGCB (93% identical), tropical clawed frog sgcb (82% identical), zebrafish sgcb (73% identical), Drosophila melanogaster Scgbeta (25% identical), Caenorhabditis elegans sgcb-1 (21% identical).
Diseases named in the same sentence as SGCB in open-access papers:
SGCB is named in the same sentence as 200 diseases in open-access papers, as found by Europe PMC text mining. Sharing a sentence is not in itself a finding about the gene and the disease. The quoted sentences say what the papers report.
sarcoglycanopathies (16 papers, 2017 to 2026). "The SGCB variant was also reported to be the most frequent in our recent study with different sarcoglycanopathies." (PMID 40225150, 2023). "Sarcoglycanopathy is the most frequent form of autosomal recessive limb-girdle muscular dystrophies caused by mutations in SGCB gene encoding beta-sarcoglycan proteins." (PMID 37699968, 2023). "Of the genes affected among sarcoglycanopathies, missense mutations are most common within the SGCB gene." (PMID 34110586, 2021). "Sarcoglycanopathies (SGPs) are limb-girdle muscular dystrophies (LGMDs) that can be classified into four types, LGMDR3, LGMDR4, LGMDR5, and LGMDR6, caused by mutations in the genes, SGCA, SGCB, SGCG, and SGCD, respectively." (PMID 39755676, 2025). "Sarcoglycanopathies (SGPs) are autosomal recessive limb-girdle muscular dystrophies (LGMDs) caused by mutations in four genes: SGCA, SGCB, SGCG, and SGCD, which lead to α-SGP (LGMDR3), β-SGP (LGMDR4), γ-SGP (LGMDR5), and δ-SGP (LGMDR6), respectively." (PMID 39755676, 2025). "Sarcoglycanopathies are caused by mutations in the SGCA, SGCB, SGCG, and SGCD genes that code for α-, β-, γ-, and δ-sarcoglycan (SG), respectively." (PMID 41009401, 2025). "Mutations in the α- (SGCA), β- (SGCB), γ- (SGCG), and δ- (SGCD) SG genes cause the four sarcoglycanopathies termed LGMD R3, R4, R5, and R6, respectively." (PMID 40549548, 2025). "Sarcoglycanopathies are caused by mutations which occur in LGMD genes SGCA, SGCB, SGCG, and SGCD that lead to misfolding, truncated, or loss of protein of α, β, γ, and δ protein which stabilizes the sarcolemma of muscle cells." (PMID 40225150, 2023). "Sarcoglycanopathies (R3-R6) are caused by missense mutations of SGCA, SGCB, SGCG, and SGCD genes, that result in misfolding of the four corresponding sarcoglycan protein subunits that form the sarcoglycan complex in the sarcolemma of muscle cells." (PMID 34110586, 2021). "Sarcoglycanopathies are caused by mutations, mostly missense, in the SGCA, SGCB, SGCG, and SGCD genes." (PMID 34110586, 2021). "Among them are sarcoglycanopathies caused by mutations in at least four genes named SGCA, SGCB, SGCG and SGCD." (PMID 28883879, 2017). "Sarcoglycanopathies include four subtypes of autosomal recessive limb-girdle muscular dystrophies (LGMDR3, LGMDR4, LGMDR5 and LGMDR6) that are caused, respectively, by mutations in the SGCA, SGCB, SGCG and SGCD genes." (PMID 34515763, 2022). "Sarcoglycanopathies comprise four subtypes of autosomal recessive limb-girdle muscular dystrophy (LGMD2C, LGMD2D, LGMD2E, and LGMD2F) that are caused, respectively, by mutations in the SGCG, SGCA, SGCB, and SGCD genes." (PMID 30764848, 2019). "Sarcoglycanopathies (SG) are the most frequent form of autosomal recessive LGMD comprising of four subtypes, LGMDR3, LGMDR4, LGMDR5, and LGMDR6, caused by mutations in SGCA, SGCB, SGCG, and SGCD encoding for the alpha-, beta-, delta-, and gamma-sarcoglycan proteins, respectively." (PMID 40225150, 2023). "The sarcoglycanopathies are a severe form of limb girdle muscular dystrophy caused by mutations in the sarcoglycan genes SGCA, SGCB, SGCG, and SGCD, leading to reduced or absent expression of the alpha-, beta-, gamma-, and delta-sarcoglycan proteins respectively." (PMID 40129306, 2025).
limb-girdle muscular dystrophy (10 papers, 2015 to 2026). Limb-girdle muscular dystrophy (LGMD) is a heterogeneous group of muscular dystrophies characterized by proximal weakness affecting the pelvic and shoulder girdles. "SGCB (sarcoglycan beta), a member of the sarcoglycan family, is associated with limb-girdle muscular dystrophy." (PMID 30918751, 2019). "Limb-girdle muscular dystrophy (LGMD) type R4/2E is caused by mutations in β-sarcoglycan (SGCB)." (PMID 37317968, 2023). "The SGCB-null mouse, with knocked-down β-sarcoglycan, develops severe muscular dystrophy as in type 2E human limb girdle muscular dystrophy with fibrosis." (PMID 26939788, 2016). "Although SGCB has been previously associated with limb-girdle muscular dystrophy, these homozygous individuals showed no biochemical or clinical signs of skeletal muscle involvement, indicating an absence of myopathy." (PMID 42222889, 2026). "In the subjects with CK ≥ 2000 U/l without DMD mutations, the most common limb-girdle muscular dystrophy (LGMD) genes were investigated and mutations in DYSF, SGCB and FKRP genes were found." (PMID 32112218, 2020). "For these individuals, mutation analysis was extended to include the seven most common limb-girdle muscular dystrophy (LGMD) genes (DYSF, CAPN3, SGCA, SGCB, SGCC, SGCD, and FKRP)." (PMID 31588416, 2017).
muscular dystrophies (8 papers, 2009 to 2025). "Mutations in the SGCB gene resulted in limb-girdle muscular dystrophies, characterized by pelvic muscle weakness and wasting, which may be involved in the pathogenesis of POP." (PMID 39902300, 2024). "An automated process has been developed for the detection of deletions, duplications/insertions and point mutations in any gene or family of genes and has been applied to ten genes known to bear mutations that cause muscular dystrophy: DMD; CAV3; CAPN3; FKRP; TRIM32; LMNA; SGCA; SGCB; SGCG; SGCD." (PMID 19835634, 2009). "Also, there were no CNVs detected in the targeted analysis of SGCA, SGCB, SGCG, SGCD, and FKRP genes for other frequent limb-girdle muscular dystrophies." (PMID 36425804, 2022).
cardiomyopathy (4 papers, 2016 to 2024). A disease of the heart muscle or myocardium proper. "LGMD type 2E (LGMD2E), with a mutation in the beta-sarcoglycan (SGCB) gene, represents a severe form of LGMD, often associated with cardiomyopathy and abnormalities in the vasculature." (PMID 28750661, 2017).
Limb Girdle Muscular Dystrophy Type 2E (3 papers, 2017 to 2022). "The SGCB gene has not previously been linked to any neoplastic disease, mutations in this gene have been associated with the development of limb-girdle muscular dystrophy type 2E." (PMID 35870994, 2022).
Beta-sarcoglycanopathy (2 papers, 2022). "The three patients harboring the pathogenic compound heterozygous variants in SGCB were eventually diagnosed with beta-sarcoglycanopathy." (PMID 35813381, 2022). "Pathogenic SGCB variants identified in our patients with beta-sarcoglycanopathy." (PMID 35813381, 2022). "Beta-sarcoglycanopathy (LGMDR4) results from biallelic molecular defects in SGCB and features pediatric onset with limb-girdle involvement, often complicated by respiratory and heart dysfunction." (PMID 36077211, 2022).
dilated cardiomyopathy (2 papers, 2022 to 2026). Cardiomyopathy which is characterized by dilation and contractile dysfunction of the left and right ventricles. "A recent study confirmed the higher prevalence of dilated cardiomyopathy in LGMDR4 presenting mono- or biallelic SGCB c.377_384dup, strengthening the existence of a phenotype–genotype correlation." (PMID 36077211, 2022).
neurological disorders (3 papers, 2018 to 2022). "Moreover, we identified 3 upregulated [ENO3, LPIN1 and SCN9A] and 3 downregulated [ATL3, CPT1C, and SGCB] RNAs whose genes have been implicated in neurological disorders." (PMID 34907471, 2022).
Mendelian diseases (1 paper, 2022). "The novel intronic SGCB variants identified in our patients emphasizes the potential role of underdetected DISVs in rare Mendelian diseases." (PMID 35813381, 2022).
SGCB also shares sentences with these, for which no sentence is quoted: pulmonary hypertension (82 papers); heart failure (60); Hypertension (47); cardiovascular diseases (38); endothelial dysfunction (31); cancer (25); diabetes (22); tumor (22); atherosclerosis (19); chronic kidney disease (17); chronic thromboembolic pulmonary hypertension (15); kidney disease (15); liver fibrosis (15); cardiac hypertrophy (12); myocardial infarction (10); breast carcinoma (9); Cirrhosis (9); renal fibrosis (9); chronic heart failure (8); ischemia (8); portal hypertension (8); Stroke (8); coronary artery disease (7); diabetic nephropathy (7); Sepsis (7); fibrosis (6); glioma (6); heart disease (6); Obesity (6); ovarian carcinoma (6).
A further 161 diseases each share a sentence with SGCB in 6 papers or fewer.